NOXO1 (NADPH oxidase organizer 1)
Diseases named in the same sentence as NOXO1 in open-access papers:
NOXO1 is named in the same sentence as 21 diseases in open-access papers, as found by Europe PMC text mining. Sharing a sentence is not in itself a finding about the gene and the disease. The quoted sentences say what the papers report.
colon cancer (6 papers, 2017 to 2026). "Eventually, while deserving further studies, in an AOM/DSS murine colon cancer model NoxO1 appeared to be protective." (PMID 29867954, 2018). "In human colon cancer cells, proteasomal degradation of NoxO1 reduces the Nox1-dependent ROS formation, and expression and stability of NoxO1 were significantly increased in human colon cancer tissues compared to normal colon." (PMID 29867954, 2018). "In mouse models of dextran sulfate sodium (DSS)-induced colitis and azoxymethane/DSS induced colon cancer, NoxO1 has a protective role and may influence the population of natural killer cells." (PMID 29867954, 2018). "In line with that, NoxO1-/- mice have less apoptotic enterocytes and develop DSS/AOM-induced colon cancer easier than wildtype mice." (PMID 32164269, 2020). "However, whether or not NoxO1 upregulation is the cause or the consequence of colon cancer remains elusive." (PMID 29867954, 2018). "Our prior results demonstrated that NOXO1 and NOXA1, in addition to NOX1, are also increased in clinical colon cancer specimens, facilitating the potential for active NOX1 activity." (PMID 28498822, 2017). "Finally, NOX1, NOXO1, NOXA1, and p22phox expression are all significantly increased in colon cancers when compared with simultaneously resected, adjacent, histologically uninvolved colonic epithelium." (PMID 28330872, 2017). "The absence of NoxO1 increased the likelihood for tumor development and the number of tumors in the AOM/DSS colon cancer model." (PMID 29867954, 2018).
atherosclerosis (5 papers, 2020 to 2026). A disease characterized by the build-up of fatty material and calcium deposition in the arterial wall resulting in partial or complete occlusion of the arterial lumen. "The cytosolic subunit NADPH oxidase organizer 1 (NoxO1) of the Nox1 complex has also been linked to inflammation and atherosclerosis." (PMID 37627585, 2023). "NADPH oxidase organizer 1 (NoxO1) is a scaffold cytoplasmic subunit of the reactive oxygen species (ROS) forming Nox1 complex and involved in angiogenesis, differentiation, and atherosclerosis." (PMID 39426288, 2024). "Here we set out to determine the role of NoxO1 for atherosclerosis development in mice using the AAV-PCSK9 overexpression system combined with a high fat diet." (PMID 32949971, 2020). "In summary, the present study suggests NoxO1 to play a minor role in promoting atherosclerosis development in female mice, which is mediated by a reduced systemic inflammatory activity." (PMID 32949971, 2020). "Collectively, these data suggest that a systemic attenuation of the inflammatory response in female NoxO1−/− mice contributes to the protection from atherosclerosis development." (PMID 32949971, 2020). "Given that humans, compared to mice, have much lower levels of systemic inflammatory activity, it is unlikely that NoxO1 is an important target for the prevention of atherosclerosis." (PMID 32949971, 2020). "The scaffolding protein NoxO1 plays some role in atherosclerosis development in female mice probably by attenuating the global inflammatory burden." (PMID 32949971, 2020). "Atherosclerosis development between NoxO1 knockout and wildtype was significantly changed in females only." (PMID 32949971, 2020). "Despite this, the overall importance of NoxO1 for atherosclerosis development appears to be limited." (PMID 32949971, 2020). "Deletion of NoxO1 reduced atherosclerosis formation in brachiocephalic artery and aortic arch in female but not male NoxO1−/− mice as compared to WT littermates." (PMID 32949971, 2020). "In the vascular system, a role of NoxO1 has been described for angiogenesis and atherosclerosis." (PMID 41406574, 2026). "The detrimental effects of Nox1 activity may be averted by the knockout of NoxO1, which has been demonstrated to safeguard female mice from atherosclerosis and to promote longevity in mice." (PMID 39334772, 2024). "Thus, additional empirical testing would have been needed, in particular an excessive amount of animal work, involving models like ovarectomy and testosterone supplementation and tissue specific NoxO1 deletion as well as other models of atherosclerosis." (PMID 32949971, 2020). "•Deletion of NoxO1 attenuated atherosclerosis development in female mice." (PMID 32949971, 2020). "For instance, female NoxO1 knockout mice exhibit a protective response against atherosclerosis when fed a high-fat diet, while male counterparts do not demonstrate a similar response (and unpublished observation)." (PMID 41406574, 2026). "Given that NoxO1 is an essential factor for Nox1-dependent ROS production, the present study to some extent supports a role for Nox1 in atherosclerosis development, although to our knowledge no gender bias has been reported for Nox1 so far." (PMID 32949971, 2020). "Furthermore, deletion of NoxO1 reduced atherosclerosis formation in brachiocephalic artery and aortic arch in female but not male NoxO1−/− mice as compared with WT controls." (PMID 37627585, 2023). "In order to differentiate this between genders and atherosclerosis, the expression of pro- and antioxidant genes was compared from the MACEseq data set: Oxidases such as Noxes, cytochrome c oxidases as well as xanthine oxidases were not altered by NoxO1 deletion (Supp.6 and Supp." (PMID 32949971, 2020).
breast carcinoma (2 papers, 2024). "A recently identified biflavonoid has been demonstrated to exert cytotoxic effects on MCF7 breast cancer cells and others through the downregulation of NoxO1 mRNA expression." (PMID 39334772, 2024). "Given the potential role of NoxO1 in cancer, as outlined in the introduction, we conducted an analysis of human colon and breast cancer cell lines (CaCo2, MCF7, and MDA-MB231) in addition to Hek293 cells, which served as an easily manipulatable model cell line." (PMID 39334772, 2024). "In a previous study, we observed that NoxO1 was moderately expressed in Hek293 cells, whereas its expression in MCF7 breast cancer cells was markedly elevated." (PMID 39426288, 2024).
colitis (2 papers, 2014 to 2018). Inflammation of the colon. "Expression of all of the subunits forming the NOX1 system, namely, NOX1, p22PHOX, NOXA1, and NOXO1, was indeed increased in the mouse model of TNFα-induced colitis." (PMID 25276054, 2014). "The observation that the expression of NOX1, NOXA1, NOXO1, and p22PHOX is increased during TNFα-induced colitis is in agreement with previous in vitro studies showing that treatment of T84 colon epithelial cells with TNFα increased NOX1 and NOXO1 expression at the mRNA and protein levels." (PMID 25276054, 2014). "This study demonstrates for the first time that TNFα-induced colitis triggers a marked increase in the expression of key components of the colon-specific NADPH oxidase isoform, NOX1, NOXA1, NOXO1, and p22PHOX." (PMID 25276054, 2014). "Colitis as such, however, appears to be more severe in the absence of NoxO1." (PMID 29867954, 2018). "Colitis, as induced by DSS, is more severe in the absence of NoxO1 in mice." (PMID 29867954, 2018).
colorectal cancer (2 papers, 2023 to 2024). A primary or metastatic malignant neoplasm that affects the colon or rectum. "The Noxo1 wt protein is predominantly present in the membrane fraction, while the mut1 Noxo1 protein is predominantly in the cytoskeletal fraction in colorectal cancer cells." (PMID 36902094, 2023). "NADPH oxidase localizes to ECM-degrading invadopodia in a human colorectal carcinoma cell line, and overexpression of p47phox family member NADPH oxidase organizer 1 (NOXO1) reduces ROS-positive invadopodia formation and ECM degradation." (PMID 39354505, 2024).
emphysema (2 papers, 2022 to 2023). "Of note, deletion of the NOX1 binding subunit NOXO1 in mice was recently found to be protective against emphysema." (PMID 36009258, 2022). "This seems to share similarities with recent findings that the deletion of the NOX1 binding subunit NOXO1 was protective against the development of emphysema in mice." (PMID 36009258, 2022). "Nox subunit NOXO1 (Nox organiser-1) was upregulated in both Nox2−/– animals and wild-type mice with cigarette smoke-induced emphysema, as well as in human COPD, whereas Noxo1−/– mice were protected from cigarette smoke-induced emphysema and PH with right heart hypertrophy." (PMID 36631133, 2023).
endothelial dysfunction (2 papers, 2019 to 2025). In vascular diseases, endothelial dysfunction is a systemic pathological state of the endothelium (the inner lining of blood vessels) and can be broadly defined as an imbalance between vasodilating and vasoconstricting substances produced by (or acting on) the endothelium. "Nonetheless, the specific role of NOX1 in mediating endothelial dysfunction was further corroborated by rejecting the notion of cross-talk between NOX1 and NOX2 in a p47phox-NOXO1 double-KO mouse model." (PMID 31382355, 2019). "To further investigate the mechanisms by which PFKFB3 contributes to endothelial dysfunction and decreased NO bioavailability, we transduced HAECs with NOX1 adenovirus (in addition to its coactivators NOXA1 and NOXO1) and either GFP (control) or wt-, cyt-, or KD-PFKFB3." (PMID 40002359, 2025). "It was found that KO of either NOXO1 or p47phox conferred the same antihypertensive effects and protection against endothelial dysfunction as the combined deletion of the two subunits, and there were no additive effects from the p47phox-NOXO1 double-KO." (PMID 31382355, 2019).
gastric cancer (2 papers, 2019 to 2021). A primary or metastatic malignant neoplasm involving the stomach. "We confirmed that Noxo1 expression is significantly upregulated in intestinal-type as well as diffuse-type human stomach cancer using a public database." (PMID 30700829, 2019). "We previously showed that suppression of NOXO1 expression by siRNA resulted in decreased colony formation of gastric cancer cells." (PMID 30700829, 2019). "We also found that NF-κB directly regulated NOXO1 expression in TNF-α-stimulated gastric cancer cells, suggesting that inflammation induces NOX1 complex activation through TNF-α/NF-κB pathway." (PMID 30700829, 2019). "Furthermore, expression of NOXO1 in human gastric cancer was positively correlated with those of TNF-α significantly." (PMID 30700829, 2019). "We next examined the mechanism of the NOXO1 induction by TNF-α using human gastric cancer cells." (PMID 30700829, 2019). "We next examined whether TNF-α signaling increases the ROS level in gastric cancer cells by induction of NOXO1 expression." (PMID 30700829, 2019). "In epithelial cells of gastric cancer and gastritis, TNF-α stimuli upregulate NOX1 and the inhibition of NF-κB/P65 by shRNA remarkably blocked the upregulation of NOXO1, which is one component forming NOX1." (PMID 33757467, 2021). "We previously reported that Noxo1 expression is induced in gastric tumors by TNF-α signaling and is important for the maintenance of tumorigenicity of human stomach cancer cells." (PMID 30700829, 2019). "Notably, in situ hybridization indicated that Noxo1 mRNA was detected in proliferating cells of gastritis and gastric tumors, and pharmacological inhibition of NOX activity significantly suppressed the proliferation of MKN45 gastric cancer cells and gastric hyperplasia of K19-C2mE mice." (PMID 30700829, 2019).
gastritis (2 papers, 2019 to 2021). Inflammation of the stomach. "Finally, the disruption of Noxo1 in K19-C2mE mice significantly suppressed gastritis-associated metaplastic hyperplasia." (PMID 30700829, 2019). "Furthermore, disruption of Noxo1 in K19-C2mE mice significantly suppressed gastritis-associated metaplastic hyperplasia, a potent preneoplastic lesion, which was associated with decreased number of SOX2-positive cells." (PMID 30700829, 2019). "Notably, expression of Nox1, Noxa1, Cyba encoding p22phox as well as Noxo1 was increased significantly in both mouse models for gastric tumors and gastritis in comparison to wild-type mouse stomach, which suggest the inflammation-dependent activation of the NOX1 pathway." (PMID 30700829, 2019). "To examine whether ROS production is induced in gastritis and gastric tumors according to the Noxo1 expression, we performed Dihydroethidium (DHE) staining using frozen sections of stomach tissues of K19-C2mE and Gan mice that developed gastritis and gastric tumors, respectively." (PMID 30700829, 2019). "Since the activation of NOX1 complex is regulated by the protein level and phosphorylation of NOXO1, NF-κB is possibly important for NOX1/ROS pathway activation both in the gastritis and gastric tumors." (PMID 30700829, 2019). "Here, we showed that expression of NOX1 complex components, including Noxo1, but not other NOX family members was significantly upregulated in both mouse models for gastritis and gastric tumors, which was associated with increased ROS levels." (PMID 30700829, 2019).
chronic granulomatous disease (1 paper, 2025). Chronic granulomatous disease (CGD) is a rare primary immunodeficiency, mainly affecting phagocytes, which is characterized by an increased susceptibility to severe and recurrent bacterial and fungal infections, along with the development of granulomas. "The NOXO1-CYBA interaction is similarly disrupted by the chronic granulomatous disease (CGD)-associated P156Q mutation in the CYBA motif 155-PPPRP-159, suggesting a similar binding mechanism as seen for the NCF1-CYBA interaction." (PMID 41463297, 2025).
diabetes (1 paper, 2020). "Moreover, after a 16-week duration of diabetes, Pggt1bΔ/Δ mice exhibited lower α-smooth muscle actin (α-SMA) and nitrotyrosine level, Rac1 activity, p47phox and NOXO1 expression, and phospho-ERK1/2 and phosphor-JNK content than wild-type mice." (PMID 32851097, 2020).
Hyperglycemia (1 paper, 2020). An increased concentration of glucose in the blood. "Moreover, we also found that lack of VSMC GGTase-I in vivo suppressed the upregulation of membrane p47phox and NOXO1 induced by hyperglycemia, and the situation was almost the same in the cytoplasm." (PMID 32851097, 2020).
lung carcinoma (1 paper, 2018). "Marked changes in gene expression were measured for Ccl2, Ccl7, Ccl17, Ccl22, Ccl3, Ccl4, Il-1α, Il-1ß, and Il-1rn (inflammation), Lpo and Noxo1 (oxidative stress), and Mmp12 (inflammation/lung cancer)." (PMID 29463257, 2018).
pancreatic cancer (1 paper, 2024). "ChIP-qPCR experiments in pancreatic cancer cell lines confirmed significant H3K18ac enrichment in NOXO1 promoter region, which was diminished upon NLRP4 knockdown, suggesting NLRP4’s regulation of H3K18ac at the NOXO1 promoter." (PMID 39187531, 2024).
tumor (7 papers, 2010 to 2024). "Using the Gan mouse model, we identified NADPH oxidase organizer 1 (Noxo1) as a TNF-α-dependent tumor-promoting factor for gastric tumorigenesis." (PMID 30700829, 2019). "In contrast, in the tumor AOM/DSS model, less macrophages were found in NoxO1−/−-deficient tumors, as analyzed by conventional immunohistochemistry and a costaining of F4/80 (Adgre1) and the Noxes on mRNA level." (PMID 29867954, 2018). "It is assumed the stimulation of the TNF-α/TNFR1 signaling in the tumor microenvironment enhances GC progression by inducing Noxo1 and GNA14." (PMID 29867530, 2018). "Conversely, genes that were under-expressed in tumor versus normal brain in animals fed a SD (Cyba, Noxo1, Prdx4 and Gpx7) were over-expressed in tumor from animals fed a KD." (PMID 20831808, 2010). "In Gan mouse tumors, Noxo1 mRNA was detected in the tumor cells in the proliferating area." (PMID 30700829, 2019). "Eventually, although not significant, there was a trend for a higher tumor burden and mortality, in NoxO1-deficient animals when compared to their WT littermates." (PMID 29867954, 2018). "Nox1 and its regulators NoxO1 and NoxA1 are expressed greater in human gastric and intestinal adenocarcinomas than in normal gastric mucosa, suggesting that Nox protein activation could be a sign of tumor transformation." (PMID 38742936, 2024). "Additionally, evidence suggests that NoxO1 plays a role in tumor formation in the stomach." (PMID 39334772, 2024). "We previously showed that NADPH oxidase organizer 1 (Noxo1), a component of NADPH oxidase 1 (NOX1), is a TNF-α-induced tumor-promoting factor in gastric tumorigenesis." (PMID 30700829, 2019). "The TNF-α/TNFR1 signaling could promote GC occurrence by inducing NADPH oxidase organizer 1 (Noxo1) and G protein subunit alpha 14 (GNA14), which are crucial in the tumorigenicity and stemness of GC cells, in tumor cells." (PMID 29867530, 2018). "Concurrently, mice lacking NoxO1 exhibit augmented angiogenesis, which may potentially enhance tumor formation." (PMID 39334772, 2024).
cancer (4 papers, 2017 to 2026). A tumor composed of atypical neoplastic, often pleomorphic cells that invade other tissues. "In inflammatory settings, TNFα induces NoxO1 expression and subsequent Nox1-dependent ROS formation, which results in the enhanced proliferation of stomach epithelial cells and eventually cancer formation." (PMID 39334772, 2024). "TNF-α is able to promote the development of cancer through activating cancer-related pathways or up-regulating Noxo1 and Gna14." (PMID 28938560, 2017). "Inversely, the deletion of NoxO1 in mice has been observed to result in a reduction in the differentiation of enterocytes and an increased susceptibility to the development of DSS/AOM-induced colitis and cancer formation." (PMID 39334772, 2024). "Consequently, the potential function of NoxO1 in cancer remains uncertain, underscoring the necessity for a more comprehensive understanding of this NADPH oxidase." (PMID 39334772, 2024). "It is possible that NoxO1 exerts pro-survival effects in cancer cells." (PMID 39334772, 2024). "The authors link this to the stabilization of Noxo1 in cancer when it may simply be an increase in expression or a very different mechanism." (PMID 36902094, 2023). "While the investigation did not ascertain whether high NoxO1 expression in cancer increases lysosomal biogenesis as well, such an effect may help to sensitize cancer cells to chemotherapy." (PMID 41406574, 2026).
degenerative diseases (1 paper, 2020). "Moreover, it has been shown that NoxO1, potentially through Nox1, promotes peroxynitrite formation, which contributes to the development of degenerative diseases like COPD." (PMID 32949971, 2020).
infection (1 paper, 2020). The state of being infected such as from the introduction of a foreign agent such as serum, vaccine, antigenic substance or organism. "In addition, Noxo1, which promotes the generation of ROS and cell death, was more expressed in the Axl−/− macrophages than that observed in the control macrophages after infection." (PMID 32611752, 2020).
inflammation (1 paper, 2010). Aberrant reaction of the microcirculation characterized by movement of fluid and leukocytes from the blood into extravascular tissues. "NOXO1 is an organiser protein that activates NADPH oxidase (NOX1) and increased Noxo1 expression may be a marker for oxidative stress during lung inflammation." (PMID 20184723, 2010).
NOXO1 also shares sentences with these, for which no sentence is quoted: gastric tumors (1 paper); pulmonary hypertension (1).